SNORD114-6 (small nucleolar RNA, C/D box 114-6)
Synonyms: 14q(II-6)
Gene: Small nucleolar RNA gene on chromosome 14 (100,957,166 to 100,957,237, forward strand). Ensembl gene ENSG00000201263.
Gene Ontology:
Biological process: RNA processing
Cellular component: nucleolus
Homologues: Orthologues: chimpanzee SNORD114-6 (100% identical). Paralogues in human: SNORD114-21 (89% identical), SNORD114-15 (86% identical), SNORD114-22 (83% identical), SNORD114-23 (82% identical), SNORD114-26 (82% identical), SNORD114-28 (82% identical), SNORD114-3 (82% identical), SNORD114-9 (82% identical), SNORD114-1 (81% identical), SNORD114-18 (81% identical), SNORD114-11 (79% identical), SNORD114-20 (79% identical), and 26 more.